MGMT (O-6-methylguanine-DNA methyltransferase)
Diseases named in the same sentence as MGMT in open-access papers (continued):
Sharing a sentence is not in itself a finding about the gene and the disease.
tumor (continued). "The number of MGMT gene promoter methylated tumors was higher in the responsive group, as expected, however, some non-methylated tumor cases turned out to be nevertheless responsive to TMZ, suggesting that our procedure could be synergistic with the classical MGMT methylation biomarker." (PMID 36132155, 2022). "In addition, methylation of MGMT and DAPK1 genes in HCC tumor tissues was significantly higher than normal tissues but not adjacent tissues, revealing that methylation of two genes may play a significant role in the early stage of hepatocarcinogenesis process." (PMID 27835605, 2016). "The frequency of the methylation in tumour tissue was 57.1% in p16, 2.4% in DAP-kinase, 23.8% in GSTP1, 90.5% in APC, 45.2% in RIZ1, 64.3% in SFRP1, 59.5% in SFRP2, 28.6% in SFRP5, 47.6% in RUNX3, and 54.8% in SOCS1, while in MGMT, no aberrant methylation was detected." (PMID 17968429, 2007). "However, several limitations still exist, as lack of MGMT promoter methylation renders TMZ largely ineffective, and the activation of cytoprotective autophagy in response to TMZ administration can power GBM chemotherapy resistance and tumor recurrence over time." (PMID 36980238, 2023).
cancer (490 papers, 2002 to 2026). A tumor composed of atypical neoplastic, often pleomorphic cells that invade other tissues. "We designed a nested case–control study, assessing potential associations between MGMT epimutations in blood from healthy individuals and subsequent risk of incident cancer." (PMID 39980037, 2025). "Treatment with TMZ causes O-6-methylguanine-DNA methyltransferase upregulation, which increases cancer resistance." (PMID 40802352, 2025). "Hypomethylation of repetitive elements in peripheral blood DNA from occupationally exposed individuals is linked to reduced MGMT promoter methylation, impairing DNA repair and increasing cancer susceptibility by hindering the repair of alkylated DNA." (PMID 40182693, 2025). "MGMT promoter methylation has been observed across several cancers and is often linked to enhanced treatment response due to impaired DNA repair capacity." (PMID 40895460, 2025). "In our previous studies with human cancer cells, we showed that this effect was caused in large part by the presence of the MGMT DNA repair protein, which confers strong chemoresistance against the DNA‐alkylating impact of TMZ." (PMID 40377133, 2025). "Associations between MGMT methylation and incident cancers were analyzed by Cox proportional hazards regression." (PMID 39980037, 2025). "Gene variants in the MGMT gene can significantly affect its DNA repair efficiency, contributing to individual cancer risk." (PMID 40895460, 2025). "Treatment with TMZ causes O-6-methylguanine-DNA methyltransferase upregulation and increases cancer resistance." (PMID 40802352, 2025). "The primary concern regarding the use of non-cancer selective MGMT inhibitors is the increased risk of myelosuppression in bone marrow cells and other normal cells, which can lead to severe hematological toxicity such as leukemia and myelodysplastic syndrome." (PMID 38254819, 2024). "In all the MGMT-deficient patient-derived models of cancer (PDMCs) that we investigated, TMZ-tolerance was RAD18-dependent." (PMID 38438348, 2024). "Specifically, MGMT promoter methylation has been associated with increased sensitivity to alkylating agents, such as temozolomide, which is used in some cancer treatments." (PMID 38522008, 2024). "Cancer chemotherapy is advancing as we understand how cellular mechanisms and drugs interact, particularly involving the enzyme MGMT, which repairs DNA damage that can cause cancer." (PMID 39055560, 2024). "This reduction has profound implications for the sensitivity of cancer cells to alkylating chemotherapy, as lower levels of MGMT are associated with an increased susceptibility to the cytotoxic effects of these drugs." (PMID 39055560, 2024). "In all of the cases and experiments, MGMT deficiency turns cells to be more sensitive to methylating anti-cancer drugs." (PMID 35281059, 2022). "Other authors described a CNN for prediction of IDH mutation, MGMT methylation, and 1p/19q co-deletion from 256 brain MRIs from the Cancer Imaging Archives Dataset including LGG and HGG." (PMID 33918828, 2021). "Epimutations in MGMT have been linked to various types of cancer, such as colorectal cancer, lung cancer, and brain gliomas." (PMID 34638292, 2021). "Loss of MGMT expression in some cancer tissues such as hepatocellular, stomach, esophagus, and bile ducts is correlated with clinicopathological parameters and poor prognosis." (PMID 33976347, 2021). "A number of studies have been conducted on the potential genetic effect of MGMT rs12917 polymorphism on its susceptibility to cancer, but the results were inconclusive." (PMID 30232235, 2018). "First, we studied the association between the MGMT rs12917 polymorphism and cancer risk via an overall meta-analysis." (PMID 30232235, 2018).
cancer (continued). "Capecitabine causes depletion of the MGMT gene, which in turn allows the cancer cells to be highly sensitive to temozolomide." (PMID 29853889, 2018). "Although there were already three meta-analyses of the MGMT rs12917 polymorphism and its role in the overall risk for cancer, expanding the sample size and employing a distinct analysis strategy led to better results in our updated pooling analysis." (PMID 30232235, 2018). "Based on the currently available data, we performed an updated meta-analysis to reassess the genetic relationship between MGMT rs12917 polymorphism and cancer risk." (PMID 30232235, 2018). "We observed conflicting conclusions about the genetic role of MGMT rs12917 polymorphism in its susceptibility to different cancers." (PMID 30232235, 2018). "Epigenetic silencing of MGMT gene by its promoter methylation at specific CpG islands results in loss of its activity in various cancers, including lung cancer." (PMID 29362385, 2018). "Development of DNA methylation biomarkers (MGMT) for the purposes of cancer screening, cancer risk assessment, and chemotherapy sensitivity prediction is currently evaluated in clinical trials." (PMID 26848521, 2016). "The DNA repair enzyme O6-methylguanine-DNA methyltransferase (MGMT) is commonly overexpressed in cancers and is implicated in the development of chemoresistance." (PMID 26603103, 2015). "We observed significant association of MGMT and p16 gene methylation with oral precancer and cancer." (PMID 24991542, 2014). "In the next sections we will provide an overview of SHOX2, PITX2 and MGMT as good examples of diagnostic, prognostic and predictive biomarkers in cancer." (PMID 25229548, 2014). "The preliminary literature search yielded 46 articles that explored the association of MGMT polymorphisms with the susceptibility to different cancers." (PMID 24086516, 2013). "A large number of case-control studies have been conducted to explore the association between MGMT Leu84Phe polymorphism and cancer risk." (PMID 24086516, 2013). "Because of its important role in human DNA direct reversal repair pathway, MGMT has attracted significant attention as a candidate susceptibility gene for cancer." (PMID 24086516, 2013). "Some studies have tried to investigate the combined effects of Lue84Phe, Ile143Val, and other polymorphisms in MGMT on cancer risk." (PMID 24086516, 2013). "Alterations in the MGMT gene impair the ability of the MGMT protein to remove the mutagenic adduct from O6-methylguanine, thereby increasing the mutation rate and the risk of cancer." (PMID 24179526, 2013). "In conclusion, we observed several significant associations of the MGMT Leu84Phe polymorphism with cancer susceptibility." (PMID 24086516, 2013). "Decreased or loss of MGMT immunohistochemical expression was found more frequently in PIK3CA-mutated carcinomas compared with PIK3CA wild-type carcinomas (35% vs. 20%, P = 0.001)." (PMID 23785428, 2013). "CpG island hypermethylation of the MGMT promoter region results in gene silencing, with loss of MGMT repair capacity thought to drive cancer progression via the emergence of genomic instability." (PMID 22645611, 2012). "Ongoing or elevated MGMT expression has been associated with resistance to alkylating agents in multiple cancer types including gliomas, astrocytomas, and melanomas." (PMID 22645611, 2012). "Decreased expression of MGMT via epigenetic silencing has been reported for many cancer types and loss of its expression can be tied to greater sensitivity to alkylating chemotherapeutic agents." (PMID 22645611, 2012). "MGMT is known to repair O-6-alkylguanine DNA lesions caused by an anti-cancer alkylator, temozolomide." (PMID 21119888, 2010).
cancer (continued). "Methylation of MGMT is associated with a reduction of its mRNA and protein expression in cancer cell lines and tissues." (PMID 19393074, 2009). "To evaluate a potential relationship of MGMT constitutional methylation and the rs16906252 genotype on cancer risk, we took advantage of the prospective Women’s Health Initiative study, designing a nested case–control study to evaluate the risk of three different major cancer forms." (PMID 39980037, 2025). "However, when its regulatory balance tips via promoter methylation, polymorphisms, or epigenetic silencing, MGMT can become a liability, fuelling cancer progression, treatment resistance, and poor outcomes across malignancies." (PMID 40895460, 2025). "However, the corrective role of MGMT means that temozolomide is generally only effective in MGMT-deficient cancers." (PMID 39941808, 2025). "MGMT specifically removes the alkyl group from the O6 position of guanine, a site that, if left unrepaired, can cause incorrect base pairing, mutations, and eventually cancer." (PMID 40895460, 2025). "Another biomarker of great clinical significance is methylation of the MGMT (O6-methylguanine-DNA methyltransferase) gene promoter, which leads to epigenetic silencing of this gene and reduces the ability of cancer cells to repair DNA damage caused by alkylating cytostatics such as temozolomide." (PMID 41465586, 2025). "On the other hand, certain polymorphisms, such as rs12917 and rs2308327, have been linked to altered MGMT expression or repair efficiency and may influence individual susceptibility to cancer or treatment response." (PMID 40895460, 2025). "Hypermethylation of the MGMT gene, which has been associated with several human cancers, following OCP exposure has been reported; therefore, PTC occurrence could be related to epigenetic alterations." (PMID 38504322, 2024). "In summary, we defined key structural features associated with MGMT inactivation, thus allowing for the design of MGMT inactivators that might improve clinical outcomes in cancer treatment." (PMID 37631385, 2023). "MGMT has also been implicated in the tumorigenesis of different types of cancer." (PMID 35723009, 2022). "In addition to its role in cancer, MGMT has been linked to inflammation, as hypermethylation of its promoter is associated with chronic inflammatory diseases and chronic infectious diseases." (PMID 35115604, 2022). "O6-methylguanine DNA methyltransferase (MGMT) is associated with cisplatin (CDDP) resistance in cancer cells; however, the underlying mechanisms remain unclear." (PMID 33397362, 2021). "Methylation of the MGMT promoter has been linked to the development of several forms of cancer." (PMID 31921306, 2019). "Studies investigating the relationships between MGMT activity and disease risk and cancer therapy outcomes have been limited by cumbersome and indirect assays that may not accurately predict MGMT activity." (PMID 30811507, 2019). "Taken together, these studies indicate that the rs16906252 SNP may affect the risk of different cancers by causing increased MGMT promoter methylation." (PMID 31225507, 2019). "MGMT is associated with resistance to alkylating agent cancer therapies." (PMID 31053733, 2019). "Epigenetic alterations like MGMT lesions and its role in drug therapy provides a platform to conceptualize mechanistic models of their predictive values to reach a census to affiliate for cancer hallmark." (PMID 29712977, 2018). "However, only few studies carried out on a Chinese population evaluated the association of the MTHFR C677T polymorphism with aberrant CpG island hypermethylation of cancer-related genes, such as p16 and MGMT, in patients with HNC." (PMID 28353639, 2017).
cancer (continued). "For this reason, loss/reduced expression of MGMT can sensitize cancer cells to alkylating agents." (PMID 26967246, 2016). "MGMT repairs the mutagenic and cytotoxic interstrand DNA crosslinks resulting after alkylating agent attack and is associated with resistance to alkylating agents in cancer therapy." (PMID 26420420, 2015). "Under the exposure of NMU, MGMT-defective mice have been seen to develop cancer, while as transgenic mice carrying extra copies of the foreign MGMT gene were less prone to the disease.The, genetic polymorphism of this enzyme has proven to be a potential risk factor for cancer." (PMID 26011121, 2015). "Subsequently, some subgroup meta-analysis might not have enough statistical power to accurately evaluate the association between the MGMT Leu84Phe polymorphism and cancer risk." (PMID 24086516, 2013). "Individuals with homozygotes (TT) of MTHFR C677T had significant risk of DNA hypermethylation of MGMT in cancer tissues [OR (95% CI)=4.27(1.76-7.84)], and a significant risk was also found in those carrying MTHFR 677CT/TT genotype [OR (95% CI)= 3.27(1.21-4.77)]." (PMID 24550949, 2013). "Several studies reported that heavy cigarette smoking could aggravate the effects of MGMT variants on cancer risk." (PMID 24086516, 2013). "Our finding showed that individuals with homozygotes (TT) of MTHFR C677T had significant risk of DNA hypermethylation of MGMT in cancer tissues [OR (95% CI)=4.27(1.76-7.84)], and a significant risk was also found in those carrying MTHFR 677CT/TT genotype [OR (95% CI)= 3.27(1.21-4.77)]." (PMID 24550949, 2013). "Also determined, that he frequency of promoter methylation of CDKN2A and MGMT was associated with a 22.9 and 29.1-fold increase in the risk to develop cancer in smoker COPD patients." (PMID 22818553, 2012). "MGMT epigenetic silencing is thought to lead to random mutations in cancer." (PMID 17266773, 2007). "Experiments using the cancer cell lines in which high-level methylation or mutation leads to diminished MGMT functions, and transgenic or gene knockout mice experiments all prove that dysfunctional MGMT is one of the main reasons why cells are sensitive to TMZ." (PMID 35281059, 2022). "Thus, MGMT is a promising therapeutic target for cancer treatments involving HR-associated DDR." (PMID 33397362, 2021). "As for MGMT, a promoter variant is associated with elevated methylation across a panel of solid cancers, and MGMT promoter methylation may contribute to an elevated cancer risk in several of these malignancies." (PMID 31225507, 2019). "However, there remains a critical need for accurate, functional assays that could be used to identify individuals with MGMT-deficient cancers." (PMID 30811507, 2019). "Mutagenic effects of alkylating agents are minimized by MGMT because if left unrepaired or mis-repaired, modifications introduced into the DNA may lead to an accumulation of mutations in the genomic DNA that may eventually lead to cancer development." (PMID 31453242, 2018). "MGMT genetic variants may explain the differences in the MGMT enzyme activity and/or levels, which in turn may lead to reduced DNA repair capacity and thus increase cancer risk." (PMID 31453242, 2018). "Fourth, as an association study, it should be noted that although our results indicated the similar positive associations of MGMT promoter hypermethylation with different types of cancer, the exact underlying mechanisms might be still diverse in different types of cancer." (PMID 28986566, 2017). "Previous studies have found that loss of MGMT protein expression is predominantly associated with hypermethylation of the promoter region in a variety of primary human cancers suggesting that inactivation of this DNA repair mechanism may be an important step in human tumorigenesis." (PMID 24991542, 2014).